FGF5 (fibroblast growth factor 5)
Diseases named in the same sentence as FGF5 in open-access papers (continued):
Sharing a sentence is not in itself a finding about the gene and the disease.
melanoma (continued). "In the past, most studies on FGFs in melanoma have concentrated on FGF2 and while - in addition to FGF2 - overexpression of FGF5 mRNA was noted in some melanoma cell lines more than two decades ago, FGF5 protein expression in melanoma tissue and its impact on melanoma growth were never investigated." (PMID 29152117, 2017). "Thus, we provide the first demonstration that FGF5 is expressed in melanoma tissue and, moreover, may support clonogenic survival and invasion in vitro and tumor growth in an in vivo model." (PMID 29152117, 2017). "Therefore, we asked whether FGF5 is expressed in human melanoma tissue and whether FGF5 expression may contribute to the malignant behavior of melanoma cells." (PMID 29152117, 2017). "In addition to autocrine effects on the tumor cells, FGF5 secretion by melanoma cells may have paracrine effects on endothelial cells and/or tumor-associated fibroblasts." (PMID 29152117, 2017). "More recent studies have shown that the majority of melanoma cell lines concomitantly overexpressed FGF2, FGF5, and FGF18 and diverse isoforms of FGFRs." (PMID 31167513, 2019). "The increased Fgf5 mRNA expression in human melanoma cells in vitro increased clonogenicity and invasion without increasing growth, while the Sox17 in seminoma and primordial germ cells is not a marker of endodermal initiation but supports latent pluripotency." (PMID 33217978, 2020). "Although FGF5 mRNA was previously found expressed in some melanoma cell lines in contrast to normal human melanocytes, neither its contribution to melanoma growth nor its expression in melanoma tissue has been investigated." (PMID 29152117, 2017). "Enhanced NFAT activity in FGF5 overexpressing cells could be a consequence of FGFR1-mediated PLCγ activation as previously reported and could contribute to enhanced melanoma growth via an anti-apoptotic activity." (PMID 29152117, 2017). "Here we demonstrate that ectopic overexpression of FGF5 in human melanoma cells with low endogenous FGF5 expression increased clonogenicity and invasion but not short-term growth in vitro." (PMID 29152117, 2017). "Despite these initial findings in melanoma cell lines and the proposed tumor-promoting role of FGF5 in other malignancies, FGF5 has not been further investigated in melanoma so far." (PMID 29152117, 2017). "To rule out the possibility that endogenous FGF5 expression occurs only in melanoma cell lines under culture conditions and may thus represent a cell culture artefact, we investigated FGF5 protein expression by IHC in a tissue microarray of human melanoma specimens." (PMID 29152117, 2017).
hepatocellular carcinoma (9 papers, 2016 to 2022). A malignant tumor that arises from hepatocytes. "MiR-188-5p inhibits cell proliferation and metastasis via targeting FGF5 in hepatocellular carcinoma." (PMID 32351327, 2020). "Hsa-miR-188-5p was shown to inhibit tumor cell proliferation and metastasis in hepatocellular carcinoma through targeting FGF5, and in prostate cancer by repressing LAPTM4B expression." (PMID 29755664, 2018). "miRNA-188-5p was significantly decreased in hepatocellular carcinoma, which suppresses tumor cell proliferation and metastasis by directly targeting FGF5." (PMID 27899092, 2016). "Besides, a fibroblast growth factor, FGF5 was also found to be targeted on miR-188-5p directly and contributed to the hepatocellular cancer progression." (PMID 33944676, 2021). "Fang et al30 reported that miR‐188‐5p suppresses tumour cell proliferation and metastasis by directly targeting FGF5 in hepatocellular carcinoma, implying that up‐regulated circMATR3 might sponge miR‐188‐5p and abolish its inhibitory effects on cell proliferation and metastasis." (PMID 32166857, 2020). "FGF8 and FGF10 are involved in embryonic liver development, FGF7 and FGF9 in repair in response to liver injury, and FGF5, FGF8, FGF9, FGF17, and FGF18 in the development and progression of hepatocellular carcinoma." (PMID 27148532, 2016). "In addition, FGF5, FGF8, FGF9, FGF17, and FGF18 play roles as paracrine signals in the development and progression of hepatocellular carcinoma." (PMID 27148532, 2016).
osteosarcoma (8 papers, 2018 to 2023). A usually aggressive malignant bone-forming mesenchymal neoplasm, predominantly affecting adolescents and young adults. "In osteosarcoma, FGF5 promotes cancer cell proliferation by activating the MAPK signalling pathway." (PMID 36447000, 2023). "It was reported that FGF5 could promote cell proliferation via activation of the MAPK signaling pathway in osteosarcoma." (PMID 36294477, 2022). "FGF5 is also significantly upregulated in osteosarcoma (OS) tissues and cells." (PMID 33536494, 2021).
glioblastoma (7 papers, 2017 to 2024). The most malignant astrocytic tumor (WHO grade IV). "siRNA-mediated FGF5 downregulation thus leads to a significant reduction in glioblastoma cell proliferation; therefore, the silencing of this factor represents a promising target for therapeutic interventions in human glioblastoma." (PMID 33352931, 2020). "This would be in agreement with our previous data in glioblastoma, where FGF5 enhanced proliferation and tube formation of endothelial cells and related data in colorectal carcinoma, where tumor cell-secreted FGF18 increased the proliferation of endothelial cells and fibroblasts." (PMID 29152117, 2017). "FGF5 is a known oncogene in glioblastoma where it promotes proliferation and inhibits apoptosis." (PMID 28333948, 2017). "The analysis revealed upregulation of oncogenes, including FGF5, TGF-β superfamily members, and ITGA-5 in glioblastoma, which were downregulated in lung adenocarcinoma patients." (PMID 38612755, 2024). "There, genes with a higher expression in glioblastoma compared to astrocytoma were VEGFA, 4EBP1, CCL2, PLAU (uPA), CXCL8 (IL8), CXCL10 (IP10), CASP8, HGF, LIF, CD40, CDCp1, TNFRSF11B (OPG), CD274 (PD-L1), IL6, CXCL1, CCL20 (MIP3α), CCL8 (MCP2), CD244, MMP1, TNFRSF9, CXCL6, MMP10, FGF5)." (PMID 35301393, 2022).
nasopharyngeal carcinoma (6 papers, 2019 to 2025). A carcinoma arising from the nasopharyngeal epithelium. "Expanding our patient cohort is critical to assess the impact of confounders, such as inflammation and other comorbidities, on FGF5 expression and its potential role as a therapeutic target for nasopharyngeal cancer." (PMID 40001587, 2025). "In nasopharyngeal carcinoma (NPC), cancer-associated fibroblast-derived fibroblast growth factor 5 (FGF5) activates fibroblast growth factor receptor 2 (FGFR2)–Nrf2 signaling, thereby dampening cisplatin-induced ferroptosis and promoting chemoresistance." (PMID 40867889, 2025). "For example, in nasopharyngeal carcinoma, CAFs secrete high levels of fibroblast growth factor 5 (FGF5), which binds to fibroblast growth factor receptor 2 (FGFR2) in tumor cells, hence inhibiting cisplatin-induced ferroptosis." (PMID 39614322, 2024). "One limitation of our study is the relatively small sample size in our cohort, which may affect the generality of our findings regarding the role of FGF5 in nasopharyngeal carcinoma (NPC)." (PMID 40001587, 2025).
prostate carcinoma (6 papers, 2013 to 2022). A carcinoma that arises from epithelial cells of the prostate gland. "To date, little is known about the role of FGF5 in the prostate or its involvement in prostate cancer or castration-resistant tumor growth." (PMID 23326489, 2013). "Moreover, in the LNCap prostate cancer cell line obtained through long-term incubation in an androgen-depleted environment, FGF5 protein levels are significantly increased, and the stimulation of AR reduces FGF5 levels in these cells." (PMID 36233155, 2022).
trichomegaly (6 papers, 2017 to 2025). "In humans, mutations in the FGF5 gene cause trichomegaly (MIM 1903309) with long eyelashes, which is inherited in an autosomal recessive manner." (PMID 40869975, 2025). "Mutations in the FGF5 gene form the genetic basis for familial trichomegaly, which is manifested as increased hair growth and abnormally long and thick eyelashes for the carriers of the mutated FGF5 gene." (PMID 34305588, 2021). "Mutations in FGF5 have been linked with trichomegaly, a pathological condition involving abnormally long eyelashes." (PMID 32758128, 2020). "FGF5 deletion in mice leads to an angora phenotype and FGF5 mutations are associated with trichomegaly in humans." (PMID 29152117, 2017).
coronary artery disease (5 papers, 2013 to 2024). "Elevated levels of FGF5 were associated with a significantly increased risk of coronary disease (P = 8.94 × 10–6 and Benjamini–Hochberg FDR = 1.47 × 10–5)." (PMID 38565889, 2024). "Of note, CAD2 has been implicated in coronary artery disease and patient death; FGF-5 has been associated with ischemic heart disease, in vitro." (PMID 24432306, 2013).
androgen alopecia (4 papers, 2020 to 2024). "Therefore, the role of FGF5 in hormonal hair loss (like telogen effluvium, androgenetic alopecia, and AA) can be studied using this model." (PMID 38891117, 2024). "Its mechanism of action in improving androgenetic alopecia is potentially associated with the increased expression of EGF, FGF5, and FGF7." (PMID 33353178, 2020). "Out of 13 SNPs included in our predictive models for hair greying, 6 (FGF5 rs7680591, RUNX1 rs68088846, IRF4 rs12203592, BRINP1 rs2416699, TEX41 rs10928235, GRID1 rs2814331) were previously associated with male pattern baldness (MPB)." (PMID 32758128, 2020). "To explore the causes of increased wool and active hair-follicle density in FGF5 KO sheep, we tested the expression levels of testosterone and DHT that cause androgenetic alopecia in the skin tissue of the KO and control groups by ELISA." (PMID 32472005, 2020). "Interestingly, previous studies have suggested that the FGF5 gene may be involved in the pathogenesis of androgen alopecia." (PMID 38891117, 2024).
Hepatic fibrosis (4 papers, 2016 to 2024). The presence of excessive fibrous connective tissue in the liver. "Hanaka and colleagues observed a noteworthy function of FGF5 and role of diet in the progression of NASH (specifically hepatic fibrosis) using Fgf5-null mice." (PMID 28974056, 2017). "Previous studies indicated potential roles of Fgf5 in the progression of hepatic fibrosis, the process of gastrulation and hair growth cycle, but the molecular basis of how Fgf5 manifests its functions has not been clearly understood." (PMID 27409080, 2016).
pancreatic cancer (4 papers, 2017 to 2021). "Expression of FGF5 is increased in pancreatic cancer and associated with the occurrence and metastasis of pancreatic cancer." (PMID 33536494, 2021). "In pancreatic cancer, FGF5 promotes pancreatic cancer cells growth through its binding to FGFR1 IIIc." (PMID 33802841, 2021).
Stroke (4 papers, 2023 to 2026). Sudden impairment of blood flow to a part of the brain due to occlusion or rupture of an artery to the brain. "Genetically predicted FURIN and FGF5 were strongly associated with BP and stroke risk, while ACOX1, FGF5, and MST1 exhibited potential causal effects on CAD." (PMID 41065563, 2026). "Among these, genetically predicted levels of four proteins—ACOX1, FGF5, FURIN, and MST1—also demonstrated evidence of potential causal associations with CAD and/or stroke, supported by observational analysis." (PMID 41065563, 2026). "Proteome-wide MR identified 242 proteins associated with BP, of which 48 were also linked to CAD or stroke, with four (ACOX1, FGF5, FURIN, MST1) also supported by genetic colocalization analyses (FDR 5% and PP ≥70%)." (PMID 41065563, 2026). "We found clear evidence for stroke risk for four loci (SH2B3, FGF5, PITX2, and KCNK3)." (PMID 37479695, 2023). "Of these, 5 proteins (ACOX1, BRAP, ERP29, FGF5, and FURIN) also showed strong colocalization with CAD and/or stroke and all had concordant direction of effects for BP and CAD and/or stroke." (PMID 41065563, 2026). "CELSR2, ABO, LPA, APOE, FGF5 and ZPR1 were related to both CHD and HF, while SH2B3 and FURIN were shared between CHD and stroke on MR analysis." (PMID 39322770, 2024).
essential hypertension (3 papers, 2019 to 2022). Hypertension that presents without an identifiable cause. "FGF5 has previously been implicated as a susceptibly region for primary hypertension, while TET2 has been implicated as an aldosterone responsive mediator of α epithelial sodium channel transcription (which has a role in BP regulation)." (PMID 35886043, 2022).
Obesity (3 papers, 2020 to 2025). Accumulation of substantial excess body fat. "Some candidate genes have been robustly reported to be associated with complex traits, such as the fat mass and obesity-associated (FTO) gene on body mass index (BMI), and the fibroblast growth factor 5 (FGF5) gene on blood pressure levels." (PMID 32457790, 2020). "Obesity has been reported to exacerbate the adverse influence of FGF5 on blood pressure." (PMID 32457790, 2020).
renal cell carcinoma (3 papers, 2017 to 2021). "Indeed, an experimentally validated fibroblast growth factor (FGF)-5-derived spliced epitope in renal cell carcinoma was experimentally shown to be generated by a transpeptidation reaction spanning 40 aa." (PMID 33072102, 2020).
Sepsis (3 papers, 2024 to 2025). Sepsis is defined as life-threatening organ dysfunction caused by a dysregulated host response to infection. "A recent study found that FGF5 protects against myocardial injury caused by sepsis by inhibiting CaMKII/NF-κB signaling." (PMID 38313013, 2024). "Furthermore, FGF5 has been implicated in cardiovascular function, as it protects the heart from sepsis injury." (PMID 40869975, 2025). "Targeted overexpression of FGF5 during sepsis-induced heart injury downregulated CaMKII and NF-κB phosphorylation, reduced oxidative stress, and pyroptosis, improving cardiac injury." (PMID 39766329, 2024). "Similarly, FGF5 conferred cardiac protection against sepsis and myocardial infarction." (PMID 39766329, 2024).
astrocytoma (2 papers, 2022 to 2023). "In addition, expression of the FGFR1 IIIc isoform and FGF5 is elevated in astrocytoma and GBM patient samples compared to non-malignant controls, and FGF5 promotes oncogenic cell growth and survival through autocrine and paracrine signalling through the FGF/FGFR signalling axis." (PMID 37130917, 2023).
atrial fibrillation (2 papers, 2025). A disorder characterized by an electrocardiographic finding of a supraventricular arrhythmia characterized by the replacement of consistent P waves by rapid oscillations or fibrillatory waves that vary in size, shape and timing and are accompanied by an irregular ventricular response. "It is likely that FGF5 may also confer an effect in atrial fibrillation via inflammatory pathways." (PMID 40538118, 2025).
colorectal cancer (2 papers, 2014 to 2017). A primary or metastatic malignant neoplasm that affects the colon or rectum. "In colorectal carcinoma in contrast, FGF5 was one of 23 genes showing elevated DNA methylation in >50% of cancer tissue compared to non-neoplastic tissue." (PMID 29152117, 2017). "While it was suggested that these genes could be used in diagnostic tests, the functional consequences of elevated FGF5 DNA methylation in colorectal cancer have not been explored at present." (PMID 29152117, 2017).
diabetes (2 papers, 2024 to 2025). "For another eight biomarkers (TNFβ, GDNF, IL-18R1, LIF-R, CD244, CD6, FGF-5, IFNγ), a significant interaction by diabetes type was observed." (PMID 39799156, 2025).
heart failure (2 papers, 2024 to 2025). Inability of the heart to pump blood at an adequate rate to meet tissue metabolic requirements. "Reverse Mendelian randomization suggested that the onset of heart failure might potentially influence the levels of four inflammatory factors, with ARTN and FGF5 decreasing after the onset of heart failure, and SLAM and MMP-10 increasing." (PMID 39726944, 2024). "Notably, the present study revealed a positive causal relationship between FGF-5 and both ICM and DCM, which may be a common risk factor for these 2 types of heart failure." (PMID 40184136, 2025). "Moreover, reverse Mendelian randomization analysis identified inflammatory factors such as ARTN, FGF5, MMP-10, and SLAM, whose increased secretion may represent an adaptive response to heart failure." (PMID 39726944, 2024).
hypertrichosis (2 papers, 2020 to 2022). Excessive hair growth anywhere on the body. "Mutations in FGF5 could cause localized hypertrichosis in human legs, arms, and eyelashes, because these sites have a low anagen:telogen ratio." (PMID 32168764, 2020).
liver cancer (2 papers, 2019 to 2024). An epithelial or non-epithelial malignant neoplasm that arises from the liver. "In patients with liver cancer, FGFs (FGF2, FGF4, FGF5, FGF9, and FGF22) are overexpressed." (PMID 31031647, 2019).
Myocardial fibrosis (2 papers, 2024). "Previous studies have suggested that the protective effect of LPL agonists on AF may be linked to chronic inflammation and myocardial fibrosis, while FGF5 may increase the risk of AF through myocardial fibrosis and structural remodeling of the atrium." (PMID 39563941, 2024).
myocardial hypertrophy (2 papers, 2023 to 2024). "The hierarchical cluster heatmap and Venn diagram indicated that 5 of 22 FGF genes (FGF1, FGF5, FGF12, FGF16, and FGF18) were associated with myocardial hypertrophy." (PMID 36871047, 2023). "Therefore, we speculate cautiously that the mechanism by which FGF5 leads to AF may be related to its promotion of myocardial hypertrophy." (PMID 38988665, 2024).
non-small cell lung carcinoma (2 papers, 2019 to 2024). A group of at least three distinct histological types of lung cancer, including non-small cell squamous cell carcinoma, adenocarcinoma, and large cell carcinoma. "FGF5 is known to promote the replication, migration, and invasion of non-small-cell lung cancer cells." (PMID 39595551, 2024).
preeclampsia (2 papers, 2020 to 2024). Preeclampsia is a hypertensive disorder of pregnancy that is characterized by new-onset hypertension with proteinuria presenting after 20 weeks of gestation, and depending on mild or severe forms may initially present with severe headache, visual disturbances, and hyperreflexia. "Further analysis of BP variants establishes that variants at MECOM/3q26, FGF5/4q21 and SH2B3/12q24 also associate with preeclampsia through the maternal genome." (PMID 33239696, 2020). "We found that the four preeclampsia associated variants at MECOM, FGF5, ZNF831, and SH2B3 are among the variants with the highest effect on all three BP traits, particularly on diastolic BP." (PMID 33239696, 2020). "We thus conclude that in addition to the variants near ZNF831 and FTO that exhibited genome-wide significance, BP variants at FGF5, SH3B2, and MECOM also associate with preeclampsia." (PMID 33239696, 2020).
triple-negative breast carcinoma (2 papers, 2018 to 2022). An invasive breast carcinoma which is negative for expression of estrogen receptor (ER), progesterone receptor (PR), and human epidermal growth factor receptor 2 (HER2). "For example, in triple-negative breast cancer, CAFs can correspond to the variation of Hedgehog in tumor cells through secreting fibroblast growth factor 5, subsequently reconstructing the ECM." (PMID 36604141, 2022).
alopecia (1 paper, 2021). Hair loss usually from the scalp. "Therefore, inhibiting the expression of the FGF5 gene or antagonizing its activity will prevent the premature termination of the anagen phase of the hair follicles, thereby preventing alopecia." (PMID 34305588, 2021).
astrocytic tumor (1 paper, 2023). A glial tumor of the brain or spinal cord showing astrocytic differentiation. "FGF5 expression was shown to be elevated in astrocytic tumors implying a role in astrogliosis." (PMID 36650549, 2023).
benign prostatic hyperplasia (1 paper, 2025). A non-cancerous nodular enlargement of the prostate gland. "Functional studies also reveal FGF5 overexpression in prostate cancer (PCa) and benign prostatic hyperplasia (BPH)." (PMID 41394119, 2025).